TNF (tumor necrosis factor)
Diseases named in the same sentence as TNF in open-access papers (continued):
Sharing a sentence is not in itself a finding about the gene and the disease.
disc degeneration (continued). "Therefore, we hypothesized that TNF‐α–induced increases in miR27a expression form a negative feedback loop to regulate disc degeneration by targeting FSTL1." (PMID 34190406, 2021).
Behçet’s disease (100 papers, 2010 to 2026). "A previous study on the Italian population reported a significant association between the TNFα -308 (rs1800629) polymorphism and Behçet syndrome susceptibility." (PMID 41346622, 2025). "We are reporting a case of Behcet's disease, which was complicated by sensorineural hearing loss and managed successfully with anti‐TNF agent Infliximab." (PMID 36254147, 2022). "Anti-TNF therapy seems to be a safe and effective option for the treatment of scleritis associated with Behcet disease." (PMID 31464918, 2019). "In the Turkish population, the TNF-∞1031C allele was associated with susceptibility to Behçet's disease." (PMID 22191081, 2012). "Likewise, a TNF SNP causing decreased TNF levels was significantly associated with decreased response to golimumab in Behçet’s syndrome." (PMID 39694914, 2025). "Therefore, the expression of miR-155 is elevated in Behcet's disease and is associated with the upregulation of TNF-α and downregulation of CTLA-4 genes." (PMID 38462628, 2024). "Previous studies have shown that increased TNF-α production caused by the A allele at rs361525 in the promoter region of TNF-α was a susceptibility factor for Behcet's disease while the A/A genotype at rs1800629 of TNF-α had a significant protective effect on Behcet's disease." (PMID 36530572, 2022). "It has already been hypothesized that there is polymorphism of the TNF-α gene in patients with Behçet's syndrome." (PMID 23071483, 2012). "In other diseases, e.g., Behcet's disease, IFNγ and tumor necrosis factor (TNF)α producton predominate." (PMID 41827822, 2026). "There is a growing body of evidence supporting the use of anti-tumor necrosis factor-alpha (TNF-α) therapy in severe gastrointestinal Behcet’s disease." (PMID 40585706, 2025). "Increasing evidence supports the use of anti-TNF-α agents in the management of refractory vasculopathic and gastrointestinal Behçet's disease." (PMID 40585706, 2025). "This is evidenced by increased levels of TNF-α mRNA in the serum and affected tissues of Behçet's disease patients." (PMID 40661890, 2025). "Interleukin (IL)-1, IL-6, and tumor necrosis factor (TNF)-α are the principal proinflammatory cytokines that contribute to inflammatory activity in patients with Behcet’s disease (BD)." (PMID 40757915, 2025). "For patients with refractory or persistent arthritis related to Behçet’s disease, azathioprine and/or TNF-alpha inhibitors are preferred over colchicine." (PMID 41367023, 2025). "Behcet's disease is characterized by a notable increase in the expression of both miR-155 and TNF-α, while the expression of CTLA-4 is significantly reduced." (PMID 38462628, 2024). "TNF inhibitors, namely infliximab and adalimumab, have demonstrated efficacy in managing several presentations of Behçet’s disease, such as ocular, joint, and mucocutaneous involvement." (PMID 38674208, 2024). "Rituximab has significantly shown improvement in cases of refractory posterior uveitis, Behcet disease and Juvenile idiopathic arthritis cases refractory to TNF-α inhibitors." (PMID 39157460, 2024). "Anti-TNFα agents are in the EULAR recommendations for managing aspects of Behcet syndrome, such as refractory eye, skin, mucosal, or neurological disease; however, they are not recommended for major vessel disease." (PMID 38146562, 2023). "Anti-tumor necrosis factor therapy is becoming the first-line treatment in Behcet’s disease and it was considered at some point in the management of this patient." (PMID 37227553, 2023). "Early control of oral infections in patients with Behçet's disease has been reported to contribute to improved disease management and the effectiveness of anti-TNF-α therapy." (PMID 37940896, 2023). "For limited reports of anti-TNF-α agents used in treating LV, we tried to figure out the related mechanism from other skin diseases that respond positively to anti-TNF-α agents, such as Behçet’s disease." (PMID 35455298, 2022).
Behçet’s disease (continued). "The management of this inaugural Behçet’s disease required a rapid initiation of high doses of intravenous corticosteroids and anti-TNF therapy." (PMID 34670612, 2021). "Tumor necrosis factor-alfa (TNF-a) antagonists are extensively utilized in the treatment of inflammatory rheumatic diseases and also shown to be effective in Behçet’s disease (BD) patients with major organ involvement." (PMID 33535732, 2021). "In particular, TNF alpha seems to be still the most attractive therapeutic target, under the light of the broad efficacy of anti-TNF drugs across sub entities, including birdshot choroiditis, sympathetic ophthalmia and Behçet ́s disease." (PMID 33634341, 2021). "In humans, elevated levels of TNF-α, IL-17, IL-1 and IL-6 have been found in the aqueous humor of patients with birdshot chorioretinopathy, Vogt-Koyanagi-Harada disease and Behçet’s disease." (PMID 33171664, 2020). "Factors associated with complete response to anti-TNF-α were the occurrence of more than five relapses before initiation of anti-TNF-α treatment and Behçet’s disease." (PMID 33171664, 2020). "The effectiveness of anti-TNF-alpha therapy was measured based on changes in Behçet’s Disease Current Activity Form (BDCAF) scores, prednisolone dosages and the immunosuppression load scores." (PMID 31296171, 2019). "Infliximab, an anti-tumor necrosis factor-alpha antibody, has been reported to have excellent efficacy for refractory uveoretinitis in Behçet’s disease (RUBD), and was approved for this indication in Japan." (PMID 30611312, 2019). "In several acute and chronic inflammatory diseases such as inflammatory bowel disease, Crohn’s disease, Rheumatoid arthritis, atopic dermatitis, and Behçet’s disease, overexpression of TNFα has been observed." (PMID 30235840, 2018). "Recently, many reports have shown the benefits of anti-TNF-α agents in the treatment of Behcet's disease." (PMID 26609459, 2015). "We describe our experience with a juvenile patient who had refractory intestinal Behcet's disease that responded to adalimumab, a fully humanized antibody against soluble TNF-α and its receptor." (PMID 26609459, 2015). "Tumor necrosis factor-alpha (TNF-α) is an important proinflammatory cytokine which plays an important role in the immunopathogenesis of Behcet's disease." (PMID 25759827, 2014). "Fourteen children (9 females, 5 males), 10 affected by JIA, 3 by idiopathic uveitis, and 1 by Behçet’s disease, were recruited in Group 1, thus receiving Adalimumab as first anti-TNF-α drug." (PMID 23587261, 2013). "Infliximab, a chimeric monoclonal antibody against TNF-α, has also been used effectively in therapy-resistant Behçet's disease, including cases resistant to etanercept." (PMID 23071483, 2012). "Recently, the anti-TNF-α agents have successfully been used in treating resistant Behçet's syndrome." (PMID 23071483, 2012). "Inflammation in Behçet's disease is thought to be mediated by cytokines derived from T-helper type 1 lymphocytes, including tumor necrosis factor (TNF)." (PMID 23071483, 2012). "Immune response genes such as the tumor necrosis factor alpha (TNF-α) gene, SUMO4 gene and IL-23R gene, have been reported to be associated with Behcet's disease." (PMID 22039410, 2011). "Both TNF-α and IL-6 have been found elevated in aqueous humour of patients with idiopathic uveitis, Behcet's disease and Fuchs' heterochromic cyclitis." (PMID 20467456, 2010). "Tumor necrosis factor-alpha (TNF-α) is widely recognized as a key player in Behçet's disease." (PMID 40661890, 2025). "Furthermore, soluble TNF receptors 1 and 2 are generated at inflammatory sites and correlate with arthritis activity in Behçet's disease, highlighting TNF-α as a promising therapeutic target." (PMID 40661890, 2025).
Behçet’s disease (continued). "Corticosteroids are often the initial treatment for Behçet's disease, and other medications such as colchicine, azathioprine, tumor necrosis factor-alpha inhibitor, cyclophosphamide, and others may also be used for induction or maintenance therapy." (PMID 39156306, 2024). "Furthermore, it has been demonstrated that, in comparison to healthy controls, the monocytes from Behçet’s disease patients produce higher levels of IL-1β, IL-6, and TNF-α." (PMID 38674208, 2024). "Given its pivotal role, TNF-α has become one of the main therapeutic targets for Behçet’s disease." (PMID 37483590, 2023). "NK cells, γδ T cells and neutrophils play a critical role in the disease, alongside Th1/Th2/T17 dysregulation and a decrease in T reg cells Cytokine studies have demonstrated elevated levels of TNF-α in Behçet’s disease, with a positive correlation between TNF-α levels and disease activity." (PMID 37483590, 2023). "In this both narrative and systemic review, we discuss the role of TNF-α in Behçet’s disease." (PMID 32349254, 2020). "The efficacy of anti-TNF-α agents on retinal vasculitis has emerged from Behçet’s disease studies." (PMID 33171664, 2020). "Although the etiology of Behcet's disease is still unknown, studies have revealed an association between tumor necrosis factor-alpha (TNF-α) and the clinical features, and the efficacy of some anti-TNF agents is reported in Behcet's disease patients." (PMID 26609459, 2015). "It has been demonstrated that neutrophils from patients with Behcet's disease constitutively express TNF-mRNA and produce increased amounts of TNF with lipopolysaccharide stimulation, which may play a key role in the generation of Th1 immune responses." (PMID 25759827, 2014). "The distribution of TNF-α genotypes in patients with Behçet disease." (PMID 24151497, 2013). "IL23R-IL12RB2 and TNF-α allelic frequencies in patients with Behçet’s disease." (PMID 24151497, 2013). "Proinflammatory cytokines, including TNF-α, are known to be elevated in active Behçet's disease, suggesting that anti-TNF-α therapy might be effective." (PMID 21352523, 2011). "It is known that in patients with Behçet syndrome (BS), the frequency of the rs1800629 wild-type GG genotype is higher in cases that respond to therapy compared to the GA genotype, suggesting a possible role of the SNP-containing genotype in affecting the anti-TNF drug response." (PMID 40725812, 2025). "Similarly, in 74 Behçet syndrome patients treated with anti-TNFα therapy, they found that the GA genotype was more frequent among non-responders, while the GG genotype predominated in responders, suggesting a possible role of rs1800629 as a predictive biomarker of treatment response." (PMID 41346622, 2025). "Clinicians should keep in mind that Behcet's disease is not uncommonly associated with sensorineural hearing loss, and that anti‐TNF and steroid‐sparing agents could help control the disease if other modalities fail." (PMID 36254147, 2022). "Every posterior uveitis in Behçet’s disease must be treated with systemic corticosteroid and immunosuppressant therapy, and severe cases (reduction of visual acuity, occlusive vascularity, and/or macular edema) justify the introduction of corticosteroids and anti-TNFα." (PMID 33622338, 2021). "In Behçet’s disease (BD), a multisystemic inflammatory disorder, TNF-a antagonists are also shown to be effective in patients with major organ involvement, refractory to conventional immunosuppressives (IS)." (PMID 33535732, 2021). "In this both narrative and systematic review, we explore the role of TNF-α in the immunopathogenesis of Behçet’s disease (BD) and the effect of treatment with TNF-α blockers." (PMID 32349254, 2020).
Behçet’s disease (continued). "TNF inhibition (typically infliximab) has circumstantial evidence suggesting efficacy in open label use for large vessel vasculitis secondary to refractory Takayasu’s arteritis, relapsing polychondritis, Behçet’s disease (also including adalimumab), and relapsing polychondritis." (PMID 28289923, 2017). "Sustained delivery of large molecules such as antibodies may be attractive, because not only anti-VEGF therapy and anti-TNFα antibody have shown excellent results in the treatment of refractory eye diseases (such as Behcet's disease), although this regimen also requires repeated cycles of therapy." (PMID 23472209, 2013). "The current study was deployed to evaluate the role of metastasis-associated lung adenocarcinoma transcript 1 (MALAT1) and miR-155, along with the inflammatory markers, TNFα and IL-6, and the adhesion molecule, cluster of differentiation 106 (CD106), in Behçet’s disease (BD) pathogenesis." (PMID 39798064, 2025). "Th22-type T cell clones from ocular samples taken from Behçet’s disease patients with active uveitis, produced IL-22 and TNF-a but not IFN-γ or IL-17." (PMID 34093536, 2021). "Additionally, other reports have shown that circulating levels of TNF-α and TNF-α2R in patients with Behcet’s disease were decreased after IFN-α treatment." (PMID 22685550, 2012). "Apart from their approved indications, anti-TNFα agents are also utilized off-label in conditions like non-infectious uveitis, sarcoidosis, Behçet disease, adult-onset Still’s disease, pyoderma gangrenosum, as well as in patients with TNF receptor-associated periodic fever syndrome (TRAPS)." (PMID 39157460, 2024). "Ophthalmologists should be aware of the possibility of rare manifestation of posterior scleritis in patients with Behcet disease, and that combined use of systemic steroids and anti-TNF-α therapy may resolve the scleritis without recurrence of inflammation." (PMID 31464918, 2019). "Infliximab (IFX), a chimeric antibody of the tumor necrosis factor (TNF)-α, is a biologics that is used for treating ocular symptoms of Behçet's disease that have not been adequately controlled." (PMID 32719682, 2020).
brain injury (99 papers, 2004 to 2026). Acute and chronic (see also brain INJURIES, CHRONIC) injuries to the brain, including the cerebral hemispheres, CEREBELLUM, and brain STEM. "In various in vitro experiment models, inflammatory factors, such as TNF-α, IL-1β, and IL-6, have been shown to be associated with CI-induced brain injury." (PMID 34867377, 2021). "Specifically, an increase in the expression of IL-10 was inversely correlated with the expression of TNF-α, the latter of which has been directly implicated in neutrophil recruitment following diverse brain injury." (PMID 28529954, 2017). "A similar activation of NF-kB has been observed in ovine hippocampus following LPS-induced peripheral inflammation and in cortex of rats with traumatic brain injury, which was also associated with increased TNF-a levels." (PMID 27853420, 2016). "The main cytokines associated with inflammation in ischemic brain injury are IL-1, TNF-α, IL-6, IL-10 and TGF-β and have been observed to be upregulated in ischemic brain injury." (PMID 25815894, 2015). "In this context, administration of resatorvid, a small molecule considered as inhibitor of TLR4-mediated pathways, has been shown to dramatically attenuate neuronal apoptosis associated to traumatic brain injury, to significantly decrease TNF-α and IL-1 β levels and to improve neurological recovery." (PMID 29438357, 2018). "Up-regulated expression of Na-K-Cl Cotransporter 1 (NKCC1) and inflammatory mediators such as tumor necrosis factor alpha (TNF-α) and interleukin-1 beta (IL-1β) has been demonstrated to be closely associated with the pathogenesis of cerebral edema resulting from a variety of brain injuries." (PMID 24916922, 2014). "Brain injury stimulates the release of TNF-α, which subsequently enhances the propagation of activated microglia and intensifies further neuroinflammation." (PMID 39152208, 2025). "It was shown that OX-A significantly improves the outcome of mice with ischemic brain injury by reducing inflammation through the modulation of Interleukin-6 (IL-6) and tumor necrosis factor α (TNF-α) in microglia." (PMID 40149526, 2025). "Researchers found that VNS significantly lowers levels of intestinal TNF while successfully preventing trauma-induced intestinal permeability and intestinal damage in a mouse model modeling traumatic brain injury." (PMID 38804299, 2024). "MTF was previously reported to induce neuroprotective effects on traumatic brain injury in rats via inhibiting microglial activation and decreasing TNF-α production in the brain." (PMID 37874393, 2023). "Elevated cytokines and other inflammatory mediators such as IL-1α, IL-6, and TNF-α were also confirmed in other studies of traumatic brain injury, in which the traumatic stress response was one of the causes." (PMID 39282512, 2023). "IL-6 and TNF-a are biomarkers of acute inflammation peaking within 24 h post sports-related concussion." (PMID 35631280, 2022). "Recent studies suggested that IL-6 can stimulate the migration of cultured cortical neurons, and that TNF-α promotes neurogenesis and brain repair in response to brain injury and infection in cultured neural stem/progenitor cells." (PMID 35742844, 2022). "Cui e Zhu44 also concluded that UTI therapy in traumatic brain injury decreased the activities of IL-1, TNF-, and NF-B." (PMID 36074399, 2022). "Network pharmacological analysis indicated that the TNF signalling pathway is likely the second most important pathway for SHD protection against ischaemic brain injury." (PMID 34985385, 2022). "Previous studies also show that cooling is accompanied by a reduction in TNF-α, IL-6, and IL-1β expressions in the setting of ischemic brain injury and neuroinflammation." (PMID 34776788, 2021). "We then observed the survival rate of engrafted hNPCs and the therapeutic effect of TNF-α-preconditioned hNPCs on brain function in HI brain injury." (PMID 32403417, 2020).